ERBB2 (erb-b2 receptor tyrosine kinase 2)
Diseases named in the same sentence as ERBB2 in open-access papers (continued):
Sharing a sentence is not in itself a finding about the gene and the disease.
lung adenocarcinoma (continued). "High-level ERBB2 amplification was identified in 0.9% of lung adenocarcinomas and correlated with HER2 protein overexpression." (PMID 41154672, 2025). "In subsequent versions of the NCCN guidelines, the panel of molecular tests was expanded to include BRAF, ROS-1, RET, ERBB2 (HER2), KRAS, and MET mutations as routine for patients with lung adenocarcinoma." (PMID 37893442, 2023). "ERBB2 exon 20 insertion is sensitive to pyrotinib and related to the therapy in patients with lung adenocarcinoma." (PMID 36499466, 2022). "Lung adenocarcinoma patient derived organoids were used to identify effective anti-cancer drugs poziotinib and pralsetinib for ERBB2 exon 20 insertions and RET fusions, respectively." (PMID 36568297, 2022). "Common driver mutations (EGFR, ALK, BRAF, ERBB2, KRAS, MET, RET, and ROS1) analysis were performed in lung adenocarcinoma tissue samples from two PEAC patients (P08 and P10) using next-generation sequencing." (PMID 35172862, 2022). "The Cancer Genome Atlas performed molecular profiling of tissue from 230 lung adenocarcinomas and found the prevalence of targetable mutations as follows: EGFR (11.3%), ALK (1.3%), ROS1 (1.7%), MET (4.3%), RET (0.9%), BRAF (7.0%), and ERBB2/HER2 (1.7%)." (PMID 35315222, 2022). "The human epidermal growth factor receptor 2 gene (ERBB2) is a proto‐oncogene that has emerged as a candidate for targeted therapies in lung adenocarcinoma patients." (PMID 36251951, 2022). "About 5% of lung adenocarcinoma patients have tumors with ERBB2 genetic alterations, with even fewer patients harboring ERBB2 amplification." (PMID 32190395, 2020). "ERBB2 20Ins were detected in four (7.8%) patients, which was much higher than that in unselected lung adenocarcinoma patients." (PMID 33505917, 2020). "MED24 not only had the highest correlation relationship (R-value) with ERBB2 in lung adenocarcinoma and in SCC, but also had a significant fold change after Erbb2 loss in mouse lungs." (PMID 31248101, 2019). "In TCGA database, 3504 genes showed a positive correlation with ERBB2 in human lung adenocarcinoma with a p-value less than 0.05." (PMID 31248101, 2019). "A total of 3415 and 3146 negatively correlated genes with ERBB2 in lung adenocarcinoma and SCC were found, respectively." (PMID 31248101, 2019). "By overlapping these upregulated genes identified in the second comparison (Ptend/dSmad4d/dErbb2d/d vs. Ptend/dSmad4d/d) with these ERBB2 negatively correlated genes, 117 and 87 genes were found in human lung adenocarcinoma and SCC, respectively." (PMID 31248101, 2019). "There were 154 genes showing an ERBB2 positive correlation between mouse lung tumors and human lung adenocarcinoma." (PMID 31248101, 2019). "More recently, comprehensive molecular profiling of lung adenocarcinoma from The Cancer Genome Atlas data has identified additional driver gene alterations, including amplifications in human epidermal growth factor receptor 2 (HER2 or ERBB2)." (PMID 28146588, 2017). "Results showed that DNA copy number abundances of EGFR, ERBB2, ERBB3, and ERBB4 had associations with overall survival in lung adenocarcinoma with EGFR-activating mutations." (PMID 26824984, 2016). "In this study, EGFR-activating mutation status and DNA copy number abundances of EGFR, ERBB2, ERBB3, and ERBB4 were measured in 261 surgically resected lung adenocarcinomas." (PMID 26824984, 2016). "According to our data, we detected similar expression levels of EGFR and ErbB2 in our HCC cells as compared to A549 lung adenocarcinoma cells, which belong to cells expressing low levels of these receptors." (PMID 24947784, 2014).
lung adenocarcinoma (continued). "The FGFR4 mutation is analogous to a reported tumor-specific somatic mutation in ERBB2 and is located in the same exon as a previously reported kinase domain mutation in FGFR4 (Pro712Thr) in a lung adenocarcinoma cell line." (PMID 17487277, 2007). "ErbB-2 and EGFR (epidermal growth factor receptor) are expressed in lung adenocarcinomas and associated with a poor prognosis." (PMID 7599067, 1995). "In addition, the inhibitor showed activity against lung adenocarcinomas driven by oncogenic ERBB2 YVMA34." (PMID 41282100, 2025). "We observed 7.6% of ERBB2 mutations in our LCINS, consistent with 2%-13% reported in other populations.1-4,6 In our series, only 5.9% of patients with lung adenocarcinoma had KRAS mutations, in accordance with other LCINS studies (4.4%-18%)." (PMID 38944844, 2024). "In addition, we detected the synergistic effect of gefitinib and BYL719 in organoids derived from a lung adenocarcinoma patient, harboring EGFR (L838V, L861Q), PIK3CA (H1047L), ErbB2 (D871N) mutations and MET amplification." (PMID 37553597, 2023). "Moreover, the synergistic effect of gefitinib and BYL719 was also confirmed in the 3D cell culture model, the in vivo model, as well as in the organoid model from a lung adenocarcinoma patient with EGFR, ErbB2, PIK3CA mutations and MET amplification." (PMID 37553597, 2023). "EGFR and ERBB2/Her2 are well-known oncogenic genes in human lung adenocarcinoma." (PMID 37513116, 2023). "All ERBB2 mutated patients were diagnosed with lung adenocarcinoma, were never smokers, and wild‐type for EGFR, KRAS, and ALK hotspot alterations." (PMID 36251951, 2022). "We also found that SD affected various signaling pathways to play a pharmacological role against the growth of lung adenocarcinoma cells, including ERBB2 signaling pathway, epidermal growth factor receptor signaling pathway, and phosphatidylinositol-mediated signaling." (PMID 35190747, 2022). "Molecularly targeted therapies improve outcome for lung adenocarcinoma patients whose tumors harbor mutant EGFR or translocated ALK, RET or ROS1, with an encouraging response for those with mutated BRAF, MET, NTRK-1 & 2 and ERBB2." (PMID 27998968, 2017). "ERBB2 exon 20 insertions were reported as analogous to EGFR exon 20 insertions and associated with primary resistance to currently approved tyrosine kinase inhibitors because of steric hindrance in the drug-binding pocket and a poor response to immunotherapies in lung adenocarcinoma _ENREF_24." (PMID 35911441, 2022). "The aim of our study was to analyze the mutational rate of EGFR, KRAS, BRAF, ERBB2 and PI3KCA in a large cohort of 2,219 unselected French patients presenting in routine clinical practice for first line treatment decision of metastatic or recurrent lung adenocarcinoma." (PMID 28881604, 2017). "As a consequence, ERBB2 CNA may be a valuable biomarker of prognosis in lung adenocarcinoma patients without EGFR-activating mutations." (PMID 26824984, 2016). "This invasiveness was reminiscent of metastatic lung adenocarcinoma fibroblasts, and pathway analysis in fibroblasts from IPF patients suggested this phenotype was mediated by ERBB2 (HER2) signaling." (PMID 39906351, 2024).
lung adenocarcinoma (continued). "ERBB2 was detected by NGS with four positives (6%, 4/69), similar to the documented 2–5% in lung adenocarcinoma." (PMID 33255238, 2020). "According to results, the overexpression of ERBB2 and ERBB3 reduced the probability of survival of clinical patients with lung adenocarcinoma." (PMID 31619200, 2019). "Five common oncogenes, Kras, EGFR, ALK, ERBB2, and BRAF are represented in more than 50 % of lung adenocarcinomas." (PMID 26884725, 2016). "Immunocytochemical analysis revealed erbB-2 and EGFR coexperession as a characteristic feature of most lung adenocarcinomas, and at levels of receptor expression present in bronchial epithelial cells." (PMID 7599067, 1995). "We have analysed a lung adenocarcinoma cell line CALU3, which has co-amplified topoisomerase II alpha and ERBB2 sequences, for the structure of the amplicon and for expression of both topoisomerase II alpha and beta." (PMID 8398710, 1993). "Lung adenocarcinoma subtypes 1–2 had the highest number of focal amplifications containing potential oncogenes (ERBB2, FGFR1, KRAS, MET), whereas LUAD-3 contained none." (PMID 33888829, 2021). "However, a study assessing CNVs in ErbB genes found that half of all lung adenocarcinomas have CNVs of EGFR, ERBB2, ERBB3 and ERBB4, with higher CNV number corresponding to poorer prognosis." (PMID 34274969, 2021). "Some studies have suggested that amplification of ERBB2 is a driver event specifically in oncogene-negative lung adenocarcinoma." (PMID 33959501, 2021). "Aberrations in human epidermal growth factor receptor 2 (HER-2, ERBB2) have emerged as oncogenic drivers and therapeutic targets in 1–4% of non-small cell lung cancer (NSCLC) and up to 6% of EGFR/KRAS/ALK-negative lung adenocarcinoma (LUAD)." (PMID 32477948, 2020). "This is even more clinically relevant since recent studies demonstrated a significant therapeutic benefit of trastuzumab (an anti-ERBB2 mAb) and of newer TKIs, such as afatinib and neratinib, which target both EGFR and ERBB2, in selected patients with lung adenocarcinoma." (PMID 28881604, 2017). "We present the first portrait of clinically actionable alterations in lung adenocarcinoma of Indian origin that includes EGFR, KRAS, EML4-ALK, AKT1, PIK3CA, FGFR4 and ERBB2, similar to that identified in other ethnic groups, and an additional subset of patients with FGFR3 mutations." (PMID 27998968, 2017). "Many other RTKs are known to play a role in lung adenocarcinoma, including ALK and ERBB2, and it is interesting to speculate that DOK2 may also inhibit lung tumorigenesis driven by those oncogenes." (PMID 24255704, 2013). "Basically, mutations involving EGFR, ERBB2 and KRAS are mutually exclusive and are thought to represent early events in the carcinogenesis of lung adenocarcinoma in never (EGFR and ERBB2) and current smokers (KRAS)." (PMID 21532835, 2010). "The growth stimulus that ligand-activated erbB-2 and EGFR provides to lung adenocarcinoma cells may establish a background of continued cell proliferation over which other critical transforming events may occur." (PMID 7599067, 1995). "A signaling pathway involving EGFR, ErbB2, ErbB3, phosphatidylinositol 3-kinase (PI3K), Akt, glycogen synthase kinase 3- β (GSK3-β), and cyclin D1 is essential for the maintenance of survival, mitosis, and invasiveness of human lung adenocarcinoma cell lines as well as to evade apoptosis." (PMID 22724003, 2012). "Despite promising preclinical data with neratinib (HKI-272; an irreversible ERBB inhibitor of EGFR and ERBB2) in the ERBB2-mutant NCI-H1781 cell line, clinical evaluation in patients with EGFR-driven lung adenocarcinomas does not support use of this inhibitor as a single agent." (PMID 23630663, 2013).
gastroesophageal junction adenocarcinoma (207 papers, 2013 to 2026). A carcinoma that arises from glandular epithelial cells of the esophagogastric junction. "The number of ERBB2 amplification cases was 503, and ERBB2 mutations were identified in 130 patients (4.1%), with the R678Q mutation detected in 40 patients (1.3% of all gastric or gastroesophageal junction adenocarcinoma cases and 30.8% of ERBB2 mutation cases)." (PMID 40699829, 2025). "Methods/Results: We investigated the ERBB2 R678Q mutation, utilizing the Center for Cancer Genomics and Advanced Therapeutics (C-CAT) database, which involved the analysis of 3116 gastric/gastroesophageal junction adenocarcinomas." (PMID 40699829, 2025). "Approximately 20% of advanced gastric or gastroesophageal junction adenocarcinomas have human epidermal growth factor receptor 2 (ERBB2, or HER2) amplification or overexpression." (PMID 39272827, 2024). "Nowadays, patients with ERBB2-positive metastasized gastric or esophagogastric adenocarcinoma qualify for a combination of chemotherapy and the monoclonal cytotoxic ERBB2 antibody trastuzumab, improving the patients’ survival compared to chemotherapeutic treatment alone." (PMID 34503107, 2021).
gastric adenocarcinoma (178 papers, 2007 to 2026). "Overexpression of the ERBB2(human epidermal growth factor receptor 2, formerly known as HER2) protein has been implicated in the development of gastric adenocarcinoma." (PMID 41341592, 2025). "Alterations in the genes involved in the RTK system, such as ERBB2 amplification, were often observed in gastric adenocarcinoma." (PMID 38672586, 2024). "Reciprocally, we performed a gain of function experiment in the gastric adenocarcinoma cell line NCI-N87 which harbours an ERBB2 amplification." (PMID 36153371, 2022). "Of those, 19 (11%) intestinal-type gastric adenocarcinomas were found positive for ErbB2 expression." (PMID 33947960, 2021). "For example, ERBB2-copy-gain is a predictive marker for anti-ERBB2 inhibitor treatment in breast and gastric adenocarcinomas." (PMID 31480645, 2019). "In one report, NCI-N87 ERBB2-amplified gastric adenocarcinoma cells were found to acquire enhanced activity of Src activity following prolonged in vitro exposure to trastuzumab." (PMID 25350844, 2014). "Although Src mutation has not been described in primary tumor samples, we propose that the Src hyperactivation should be investigated in the settings of acquired resistance to ERBB2 inhibition in esophageal and gastric adenocarcinoma." (PMID 25350844, 2014). "Furthermore, mutations in KMT2D, ERBB2/3, and RNF43 are also observed in both G-EAC and gastric adenocarcinoma." (PMID 40432921, 2025). "Additionally, in 2008, ERBB2 testing guidelines in advanced esophago-gastric junction and gastric adenocarcinomas were established to identify suitable patients for trastuzumab therapy." (PMID 37173881, 2023). "Using the same MS-based approach on a fresh-frozen tissue section of an ErbB2-positive gastric adenocarcinoma, the N124 glycosylation site was successfully validated and found to be occupied by Man9 glycan species, in agreement with observations made for GC cell line-derived ErbB2." (PMID 33947960, 2021). "In genomics, ERBB2, VEGFA, GATA4 and GATA6 gene amplifications were frequently observed in Barrett’s adenocarcinomas, which strongly resemble the chromosomally unstable variant of gastric adenocarcinoma." (PMID 33087057, 2020). "ERBB2 amplification for anti-ERBB2 inhibitor treatment in breast and gastric adenocarcinomas, EGFR amplification for anti-EGFR inhibitors, MET amplification for MET tyrosine kinase inhibitors, and FGFR2 amplification for FGFR2 phosphorylation inhibitors have been reported as predictive markers." (PMID 23936009, 2013). "ERBB2 is an important receptor tyrosine kinase in cancer and amplification of this locus has been identified as a therapeutic target in cancers such as breast and gastric adenocarcinoma." (PMID 23737949, 2013). "Additionally, colorectal adenocarcinomas had a decreased ERBB2/HER2 alteration rate of 5.1%, but had a similar percentage (66%) of ERBB2 amplifications as gastric adenocarcinomas." (PMID 35267592, 2022). "While demonstration of these mutations is not required clinically, testing oesophageal and gastric adenocarcinomas for ERBB2 [human epidermal growth factor receptor 2 (HER2)] is recommended, as this influences treatment decisions." (PMID 31433515, 2020). "Up to 30% of esophago-gastric adenocarcinomas have ERBB-2 (or HER2) oncogenic amplifications, which have been successfully clinically targeted with a combination of systemic chemotherapy and anti-HER2 therapy in the form of trastuzumab for almost a decade, as demonstrated by the ToGA trial." (PMID 36678598, 2023).
gastric adenocarcinoma (continued). "In conclusion, our results showed that MUC4 is overexpressed in gastric adenocarcinoma tissues, and that it has a role in promoting aggressive properties in poorly differentiated gastric non-SRCC cells through the activation of the ErbB2 oncoprotein." (PMID 18781152, 2008). "UWG02CTC also showed higher expression than UWG01CTC of targetable pathways including EGFR, FGFR2, HER-2 (ERBB2), and MET, as well as key genes in the JAK/STAT pathway, genes which overexpression are frequently reported in gastric adenocarcinomas but not gastrointestinal neuroendocrine cancers." (PMID 31953491, 2020).